GGH (gamma-glutamyl hydrolase)
Diseases named in the same sentence as GGH in open-access papers (continued):
Sharing a sentence is not in itself a finding about the gene and the disease.
tumor (continued). "Taken together, these results indicate that GGH may drive UCEC tumor progression by engaging multiple interacting molecular pathways involved in cell proliferation, migration, metabolism, apoptosis, and immune responses." (PMID 35082830, 2021). "Finally, we analyzed the associations between GGH expression level and the infiltration of various immune cell types into the UCEC tumor microenvironment." (PMID 35082830, 2021). "Further, GGH overexpression may reduce tumor immune attack by altering the immunocyte infiltration profile." (PMID 35082830, 2021). "Whether these differences in MTX-PG levels between normal and tumor cells were correlated to different levels of FPGS / GGH activity or a different cytotoxic response to MTX and/or LV has never been investigated." (PMID 32998716, 2020). "In particular, the gene expression level of GGH in tumor tissues may be a useful biomarker for determining which regimen, S-1 or UFT/LV, should be used for CRT." (PMID 28417167, 2017). "GGH upregulation reduces folic acid levels in tumor cells; thus, leucovorin combination therapy may reduce the risk of lymph node metastasis." (PMID 28915696, 2017). "Actually, we previously reported that the gene expression levels of folylpolyglutamate synthase (FPGS) and gamma-glutamyl hydrolase (GGH) in tumors could predict the levels of reduced folate after LV administration in tumor tissue." (PMID 28417167, 2017). "In particular, the gene expression level of GGH in tumor tissues may be a useful biomarker for the appropriate use of S-1 and UFT/LV in CRT." (PMID 28417167, 2017). "The five discordant tumor samples had high GGH protein levels despite low GGH mRNA levels." (PMID 23374458, 2013). "In addition, the mRNA expression of GGH and ECGF1 was associated with characteristic clinicopathological and molecular features of CIMP+, including proximal tumour site, TILs and BRAF mutation." (PMID 18414409, 2008). "In addition, GGH also acted as a novel HuR binding partner during the tumor process." (PMID 40831251, 2025). "Thus, the lower NK CD56bright cell infiltration under elevated GGH expression may also allow for tumor progression unchecked by immune attack." (PMID 35082830, 2021). "Therefore, the low levels of GGH mRNA might lead to an elevated folate level in tumor tissue, thereby enhancing the antitumor effect of UFT/LV chemotherapy." (PMID 28417167, 2017). "Since GGH is the terminal enzyme responsible for de-glutamylation of folate species and subsequent release from the cell, this may reflect an increased turnover of folates in tumor tissues relative to normal tissues." (PMID 23880844, 2013). "Future study may focus on identifying the specific binding sites of GGH signal domain with RNA, potentially leading to the discovery of small molecule targeted drugs that can effectively inhibit GGH's RNA‐binding activity, thereby achieving the goal of tumor growth suppression." (PMID 40831251, 2025). "Collectively, GGH, as a novel RBP, formed a ternary complex with HuR and mRNA targets to stabilize RNAs, maintained the cell cycle and DNA replication, and promoted tumor growth in NSCLC." (PMID 40831251, 2025). "Thus, GGH knockdown could also trigger autophagy of tumor cells in vivo." (PMID 40268350, 2025). "Depending on tumor location, the expression of ABCC3, AMT, GGH, and RFC-1 in mucosa, as well as the tumoral expression of AMT, GGH, PCFT and RFC-1 differed." (PMID 39998667, 2025). "To validate the expression of GGH in LUAD, we used immunohistochemistry (IHC) on a tissue microarray to analyze tumor cell‐specific GGH protein levels across a panel of 74 patient‐derived LUAD samples and the paired adjacent normal tissues." (PMID 40831251, 2025). "In vitro experiments revealed a significant upregulation of GGH in LUAD, and its knockdown markedly inhibited tumor cell proliferation, migration, and invasion." (PMID 38601163, 2024).
tumor (continued). "The GGH expression level was also a significant predictor of DSS for the clinical Stage I subgroup, the residual tumor R0 subgroup, and the CR subgroup, while high GGH expression had no prognostic value for PFI in any subgroup." (PMID 35082830, 2021). "Using disease-free survival as a marker for clinical outcome, this group evaluated the ability of GGH, emmprin, survivin, and DBI expression in tumor tissue to stratify 27 patients treated with neoadjuvant MVAC." (PMID 33050010, 2020). "After LV injection, a significantly higher gene expression level of GGH, MTHFD1L, SLC19A1/RFC-1, and FPGS was seen in tumour tissue compared to mucosa." (PMID 30269276, 2018). "The results of the study showed that tumour tissue of untreated patients had higher expression of FPGS, GGH, MTHFD1L, and SLC19A1/RFC-1 compared with mucosa, whereas expression of ABCC3/MRP3 and SLC46A1/PCFT was higher in mucosa compared with tumour." (PMID 30269276, 2018). "In untreated patients, the expression of GGH and MTHFD1L was significantly higher in tumour tissue compared to mucosa." (PMID 30269276, 2018). "After LV injection, the expression of FPGS, GGH, MTHFD1L, and SLC19A1/RFC-1 was significantly higher in tumour tissue compared to the mucosa." (PMID 30269276, 2018). "There was a negative correlation between 5-MTHF concentration in plasma of untreated patients and expression of GGH and SLC46A1/PCFT in tumour." (PMID 30269276, 2018). "The expression levels of four genes (HIF1A, MTHFD1, GGH and TYMS) in tumor tissue before CRT can predict the response to preoperative CRT including S-1 or UFT/LV." (PMID 28417167, 2017). "The expression levels of four genes, HIF1A, MTHFD1, GGH and TYMS, in tumor tissues can predict the response to preoperative CRT including either S-1 or UFT/LV." (PMID 28417167, 2017). "The expression of ABCC3, AMT and PCFT (p < 0.0001) was higher in mucosa compared to the tumor tissue, whereas the expression of FPGS (p < 0.0001), GGH (p < 0.0001), MFT (p < 0.01), RFC-1 (p < 0.0001) and TYMS (p < 0.0001) was lower in mucosa compared to the tumor tissue." (PMID 39998667, 2025). "We then performed ROC analysis to measure the capacity of GGH expression level to distinguish UCEC tumor tissues from nontumor tissues." (PMID 35082830, 2021). "This ubiquity of GGH overexpression in cancer suggests important contributions to tumorigenesis and (or) progression, and the relative elevation appeared higher in UCEC than many other tumor types." (PMID 35082830, 2021). "Hence, for these 7 genes (TS, FPGS, GGH, DHFR, ERCC-1, TOPO-1, and EGFR), evaluation of their expression by biopsy would reflect the mRNA expression in the whole tumor and would therefore permit their use in the clinic." (PMID 23577026, 2013). "In the present study, we found that the elevated cytoplasmic protein levels of GGH were mainly localized to the tumor cells in comparison to adjacent non-cancerous cells." (PMID 23374458, 2013). "Low expression of GGH was one of the features associated with CIMP+ CRC; however, it was not a specific marker for this phenotype because many CIMP− tumours also showed low expression of this gene." (PMID 18414409, 2008). "In the present study, both FPGS and GGH were expressed at higher levels in tumors compared to mucosa, indicating an increased intracellular folate turnover in tumors, a finding further supported by the high expression of the proliferation marker TYMS in tumor tissue." (PMID 39998667, 2025). "Furthermore, the protein levels of GGH and FAAH were significantly correlated in tumor tissues." (PMID 23374458, 2013).
cancer (21 papers, 2006 to 2026). A tumor composed of atypical neoplastic, often pleomorphic cells that invade other tissues. "Studies have shown that GGH is upregulated in multiple cancer types and associated with the phenotype and poor prognosis of some of these tumors." (PMID 40268350, 2025). "Results of GSEA analysis also revealed the associations of GGH with other cancer-related molecular pathways, including DNA replication, cell cycle, MAPK, KRAS, STAT3, and B cell receptor." (PMID 35082830, 2021). "High expression of GGH is associated with severe clinicopathological features and poor prognosis of several cancers." (PMID 35082830, 2021). "A prognostic impact of GGH expression was only seen in Gleason 4 + 3 = 7 cancers (p = 0.0265), but this association disappeared if Gleason 4 + 3 = 7 cancers were further subdivided according to their percentage of Gleason 4 fractions." (PMID 28146062, 2017). "Overexpression of GGH may be associated with dysregulation of multiple cancer-related gene pathways, including those involved in cell cycle regulation, cell motility, MAPK, STAT3, and KRAS signaling, and immune responses." (PMID 35082830, 2021). "Notably, the association between GGH expression and different cancer forms has been previously reported." (PMID 23374458, 2013). "Furthermore, our experiments validated that GGH functioned as a cancer-causing gene that could potentially enhance the advancement of LUAD." (PMID 38601163, 2024). "GGH‐bound mRNAs were enriched for diverse diseases, protein transport, maturation, degradation and pathways crucial for cancer progression, including autophagy, cell cycle, and cellular senescence." (PMID 40831251, 2025). "GGH is a key element in antifolate pharmacology and folate metabolism since it dynamically controls its activity in cancer cells." (PMID 40270992, 2025). "GGH (Gamma‐glutamyl hydrolase) is a folate metabolism enzyme that hydrolyzes intracellular polyglutamylated folates and is highly expressed in various cancers." (PMID 40831251, 2025). "Studies also showed that low GGH expression in cells can increase the chemosensitivity of cancer cells to antifolate drugs such as methotrexate, whereas high GGH expression is related to cell resistance to antifolates." (PMID 35082830, 2021). "The GGH mRNA expression levels were higher in cancer tissue (0.478 [0.000–52.951]) than in adjacent normal mucosa (0.000 [0.000–6.597] P < 0.001)." (PMID 31754833, 2020). "Several studies have previously reported that patients with high levels of GGH mRNA expression in cancer tissue resulted in significantly poor outcomes compared to patients with low levels of GGH mRNA expression." (PMID 31754833, 2020). "Given the central need for GGH in DNA replication, it can be assumed that increased cell proliferation—a typical feature of malignant tumors—should go along with higher levels of GGH in the respective cells." (PMID 28146062, 2017). "The small prognostic difference between cancers with high or low GGH expression limits its clinical impact as a stand-alone marker." (PMID 28146062, 2017). "GGH overexpression is also of interest for anti-cancer therapies, as it was found to confer resistance to fluorouracil (5-FU)-based chemotherapies in several cancers." (PMID 28146062, 2017). "Elevated plasma level of GGH was observed in patients with metastatic breast cancer in comparison to control subjects and to patients with cancer in remission." (PMID 23374458, 2013). "This cluster expressed genes specific to basal-like and normal-like cancer subtypes, including keratin-5, keratin-17, and GGH." (PMID 17054791, 2006). "We demonstrated that reduced GGH expression could induce autophagy and autophagic cell death in a wide variety of cancer and lung epithelial cells." (PMID 40268350, 2025). "Future studies may focus on understanding the relationship between GGH and cancer progression from the perspective of RNA centers, which may provide new mechanisms and methods for cancer diagnosis and treatment." (PMID 40831251, 2025).
cancer (continued). "Additionally, GGH directly interacts with HuR (Human Antigen R), a well‐characterized RNA‐binding protein critical for mRNA stability in cancer." (PMID 40831251, 2025). "Taken together, these data not only confirmed that GGH bound directly to RNAs and stabilized mRNAs, but also suggested that GGH bound to a group of mRNAs that could regulate cancer development via cell cycle and DNA replication pathways." (PMID 40831251, 2025). "GGH staining was considered as low intensity in 49.6% and as high intensity in 38.6% of cancers." (PMID 28146062, 2017). "In addition, GGH mRNA expressions were also highly expressed in different cancer types." (PMID 40831251, 2025). "The dysregulation of several cancer-related gene pathways, such as those governing cell cycle, cell motility, MAPK, STAT3, KRAS signalling and immunological responses, may be linked to the overexpression of GGH." (PMID 40270992, 2025). "Therefore, the modulation of GGH may affect the chemosensitivity of cancer cells, and exogenous folate levels may further modify this effect." (PMID 34200242, 2021). "Further analysis revealed that these associations were merely driven by the subset of ERG-negative cancers, High GGH expression was weakly linked to early biochemical recurrence in ERG negative cancers (p < 0.0001) and independent from established histo-pathological parameters." (PMID 28146062, 2017). "Gamma-glutamyl hydrolase and CFHR1 were the most strongly upregulated proteins in the TC group, with ratios (cancer/control) of 4.669 and 7.799, respectively." (PMID 32704452, 2020). "Several previous studies have compared the relative expression levels of GGH and FPGS mRNA between various types of cancer tissue and adjacent normal tissue." (PMID 31754833, 2020). "Since GGH showed differential expression in ERG-positive and ERG-negative cancers, we also analyzed both subsets separately." (PMID 28146062, 2017). "Interventions targeting GGH to regulate folate metabolism and the proportion of NADH/NAD+ may have translational potential for precision therapy in human cancer." (PMID 40268350, 2025). "GGH silencing could also activate AMPK through LKB1 and CAMKK2 phosphorylation in various cancer cell lines and normal lung cells." (PMID 40268350, 2025). "In earlier studies we had described several molecular features that were either prognostic in ERG positive (for example, SOX9, and SENP1 or in ERG negative cancers (for example, GGH and NBS1) but not in both groups." (PMID 31043167, 2019). "High-level GGH expression was found in 19.9% of cancers without detectable AR expression, but in 44.6% of tumors with strong AR expression (p < 0.0001, each)." (PMID 28146062, 2017). "Given that the prognostic difference between cancers with negative/low or high GGH expression was only about 10%, GGH does not seem to be strong prognostic marker if analyzed on its own." (PMID 28146062, 2017). "The average Ki67LI increased from 2.0 ± 0.1 in cancers lacking GGH expression to 2.7 ± 0.05 in cancers with low and to 3.1 ± 0.06 in cancers with high GGH levels (p < 0.0001)." (PMID 28146062, 2017). "Subgroup analysis of ERG-negative and ERG-positive cancers revealed that these associations were merely driven by the subset of ERG-negative cancers, while there was no unequivocal impact of GGH levels on the deletion status in ERG-positive cancers." (PMID 28146062, 2017). "Thus, GGH and FPGS strongly influence DNA synthesis in cancer cells." (PMID 31754833, 2020). "Subset analyses revealed a similar 10-year PSA recurrence-free survival of 62% for high GGH expression in ERG negative and positive cancers." (PMID 28146062, 2017).
infection (1 paper, 2019). The state of being infected such as from the introduction of a foreign agent such as serum, vaccine, antigenic substance or organism. "Data on the role of GgH in bacterial survival, dormancy and infection are still lacking." (PMID 31316802, 2019).
GGH also shares sentences with these, for which no sentence is quoted: endometrial carcinoma (2 papers); pancreatic cancer (2); Stroke (2); thymoma (2); adrenocortical carcinoma (1); alcohol use disorders (1); bipolar disorder (1); bladder cancer (1); cervical cancer (1); cocaine use disorder (1); diffuse large B-cell lymphoma (1); endometriosis (1); esophageal squamous cell carcinoma (1); fibrosarcoma (1); gallbladder cancer (1); gynecologic cancers (1); Huntington disease (1); ischemic stroke (1); large cell lymphoma (1); melanoma (1); metastatic melanoma (1); Moyamoya disease (1); neurodegenerative disease (1); neuroendocrine carcinoma (1); non-small cell lung carcinoma (1); osteosarcoma (1); ovarian serous cystadenocarcinoma (1); renal carcinoma (1); renal cell carcinoma (1); rheumatoid arthritis (1).
A further 5 diseases each share a sentence with GGH in 1 paper.